ENSG00000273291 (novel protein)
Gene: Protein-coding gene on chromosome 3 (42,809,446 to 43,055,871, forward strand). Ensembl gene ENSG00000273291.
Genetic constraint (gnomAD): Loss-of-function variants: 4 observed, 5.4 expected, observed/expected ratio (o/e) 0.74, 90% interval 0.36 to 1.61. That is too few expected variants to judge how well the gene tolerates losing a copy. Missense variants: 109 observed, 89.93 expected, observed/expected ratio (o/e) 1.21, 90% interval 1.04 to 1.42. Synonymous variants: 38 observed, 38.74 expected, observed/expected ratio (o/e) 0.98, 90% interval 0.76 to 1.29.